VIM (vimentin)
Diseases named in the same sentence as VIM in open-access papers (continued):
Sharing a sentence is not in itself a finding about the gene and the disease.
tumor (continued). "Our study found less membranous E-cadherin, more cytoplasmic vimentin, and more membranous EGFR in primary tumor samples with LNM than in those without LNM." (PMID 27172790, 2016). "We observed that the expression of 10 of 12 CSC-related markers (CD90, ALDH1, CK7, CK19, OCT4, SOX2, vimentin, nestin, CD13 and EpCam) was not significantly different between the tumor tissues and peritumoral tissues." (PMID 27329727, 2016). "Tumor cells in the elevated and atrophic plaques stained positive for CD34 and vimentin and stained negative for factor XIIIa and α-smooth muscle actin." (PMID 26932148, 2016). "In the tumor, epithelium close to the stroma shows positive staining for CD44 (A), whereas staining with vimentin (B) or E-cadherin (C) is negative at that site, this is indicated with arrows." (PMID 27590006, 2016). "Unlike intracellular vimentin, which is found in both cancer cells and normal mesenchymal cells, CSV is tumor specific." (PMID 27713131, 2016). "Immunohistochemical stainings of the primary tumor and the xenograft of OCUP-A1 and OCUP-A2 were negative for E-cadherin, but almost positive for vimentin." (PMID 27067801, 2016). "Immunohistochemical studies in three cases demonstrated that the tumor cells were positive for CD34, vimentin, SMA, and HMB-45, but negative for S-100." (PMID 26391670, 2015). "The tumor in our case was diagnosed as a type 2 PRCC due to its morphological features, lack of expression for CK7, and positivity for EMA, Vimentin, and AMACR." (PMID 26301110, 2015). "Immunohistochemical examination indicates that the tumor cells were diffusely positive for Factor VIII, Fli-1, CDK4, INI-1, MDM2, vimentin, focally positive for AE1/AE3, CD31 and negative for actin-sm, CD34, desmin, myoD1 and S-100." (PMID 26315812, 2015). "The tumor cells expressed CD34, bcl-2, CD99, and vimentin and were negative for LCA (leukocyte common antigen), desmin, SMA (smooth muscle antigen), CK7, CK34, BE12, CK19, and CK20." (PMID 25688313, 2015). "Despite the inhibitory effect of miR-200b in the tumor invasion of ESCC, the expression of neither E-cadherin nor vimentin was appreciably altered by the miR-200b mimic in the xenografts." (PMID 26334393, 2015). "Immunohistochemical staining revealed that the tumor cells were positive for epithelial membrane antigen (EMA) and vimentin, and negative for CD34, bcl-2, SMA, and S-100 protein." (PMID 25896915, 2015). "The tumor was immunonegative for GFAP and Syn, whilst it was immunopositive for vimentin, EMA, S-100 and TTF-1." (PMID 25777996, 2015). "The coordinated upregulation or, not uncommonly, overexpression of ZEB1, ZEB2, SNAI1, and VIM and the downregulation of CDH1 indicated that EMT was under way, making the tumor cells assume a mesenchymal phenotype." (PMID 25157365, 2014). "Normally, the tumor cells are positive for MIC-2 (CD99) and vimentin, and negative for desmin and CK, but are not specific markers for pPNET." (PMID 25013495, 2014). "On a detailed immunohistochemical analysis, the tumor cells were intensely positive for smooth muscle actin (SMA), moderately positive for vimentin and negative for CD34 that was positive only in the vessels endothelium." (PMID 25408738, 2014). "Whereas other indicators, such as CK, vimentin and SMA, demonstrate a negative expression and signal the presentation of other types of tumours." (PMID 24959253, 2014). "In the present case, immunohistochemistry revealed that the tumor was positive for GFAP, S-100 protein, vimentin, CD34, CD99 and D2-40 and negative for neuron markers (Syn and chromaffin protein/NeuN)." (PMID 24348765, 2014). "If tumor cells are not immunoreactive for either the S-100 protein or EMA, but are positive for vimentin, CD10, and CD34, these cells are considered to correspond to endoneurial fibroblasts." (PMID 24112233, 2013). "Immunoreactivity for vimentin and smooth muscle actin (SMA) was detected in the cytoplasm of the tumor cell, but not for desmin or cytokeratin." (PMID 23936706, 2013).
tumor (continued). "This tumor was classified as an undifferentiated myxoid sarcoma based on the lack of a glial proliferation, strong CD68 and vimentin immunolabeling in the majority of tumor cells and the absence of CD1a and GFAP immunolabeling." (PMID 24073000, 2013). "In the MA area, tumor cells showed positive diffuse staining for CD57, WT-1, focal staining for vimentin, pan CK, CK7 and CK8/18, but negative staining for epithelial membrane antigen (EMA)." (PMID 23599785, 2013). "Immunohistochemical staining showed that the tumor cells were strongly positive for glial fibrillary acid protein (GFAP), vimentin, and S-100 protein, but negative for neurofilament." (PMID 23187747, 2013). "Immunohistochemically the tumor cells express desmin, SMA and vimentin but not S-100 or cytokeratin." (PMID 23421917, 2013). "Of the two cases whose tumor cells were not immunoreactive for the S-100 protein, one case was in our group, and his tumor cells were positive for CD34 and vimentin, suggesting the tumor is not conventional Schwann cell-derived MPNST." (PMID 24112233, 2013). "Immunohistochemically, the tumor was positive for CD99, vimentin, neuron specific enolase and chromogranin A, and negative for cytokeratins, CD3, desmin, and leukocyte common antigen." (PMID 23537038, 2013). "Positivity within tumors was significantly correlated with collagen IV and vimentin expression, suggesting a role of SPON1 in the reorganization and remodeling of tumor extra cellular matrix (ECM) (data not shown)." (PMID 24133572, 2013). "In the WT area, tumor cells stained diffusely for WT-1, CK8/18, focally for vimentin, pan CK, EMA, CD57, but were negative for CK7." (PMID 23599785, 2013). "In our experience the vimentin/EMA/CD10 combination bound to both the stroma and epithelial tumour area, unlike the optimal tumour masking strategies developed following our optimisation strategy." (PMID 22363672, 2012). "The tumor cells expressed CD1a, Langerin (CD207), S-100 protein, CD68 and vimentin, and did not express pan-T or B cell markers and epithelial markers." (PMID 22889043, 2012). "Immunohistochemically, the tumor was positive for CD31, CD34, and Vimentin, a mesenchymal marker, and negative for HAS and GPC-3, which excluded the possibility of hepatocyte origin." (PMID 22280556, 2012). "Both CK-positive and -negative tumour cells coexisted within a CTM, and this within CTM heterogeneity was also observed for both E-Cadherin and Vimentin." (PMID 22187035, 2012). "This was in contrast to the mouse antibody vimentin which only bound stroma or renal cell marker (RCC) which was non-selective, binding both tumour and stromal areas equally." (PMID 22363672, 2012). "There was no statistical difference in neoplastic cell vimentin expression between early-stage (stages T1 or T2 TNM) and advanced tumours (TNM stages T3 or T4)." (PMID 21448168, 2011). "This tumor displayed CD10 negative, chromogranin positive, synaptophysin positive, and vimentin weak positive findings on immunohistochemistry which led to a pathological diagnosis of well differentiated benign cystic PET." (PMID 21771323, 2011). "In our case, the tumor cells were strongly positive for CD34, CD99, Bcl-2, and vimentin and negative for smooth muscle actin (SMA), CD31, cytokeratin, S-100, CD117, and epithelial membrane antigen (EMA)." (PMID 21443810, 2011). "The phenotype detected here in CTCs therefore strongly differed from that detected in primary tumours in NSCLC patients, which are positive for pan-keratin antigens and negative for vimentin." (PMID 21970878, 2011). "Immunohistochemically, the tumor cells were strongly positive for CD34, CD99, Bcl-2, and vimentin and negative for smooth muscle actin (SMA), CD31, cytokeratin, S-100, CD117, and epithelial membrane antigen (EMA)." (PMID 21443810, 2011). "We therefore concluded that the desmin-positive, vimentin-positive cells were typical pericytes, rather than VSMC, coating the tumor micro-vessels." (PMID 22141345, 2011).
tumor (continued). "The spindle-shaped tumor cells constituting most of the tumor were not reactive for CK AE1/AE3, but instead were strongly positive for vimentin." (PMID 20731838, 2010). "The tumor tissues showed a positive reaction for CD117, CD34 and vimentin, but not for desmin, PLAP, S-100, SM-actin, NF, GFAP, NSE, HMB-45, and SC-actin." (PMID 19500398, 2009). "This tumor showed negative staining for RCC, vimentin, CD10 and smooth muscle actin, which does not support a metastatic lesion with renal or myoepithelial cell origin." (PMID 17338818, 2007). "It is characterized by tumor extension into perirenal fat tissue and invasion of the renal vein and inferior vena cava and is immunohistochemically characterized by positive staining for CA-IX, CD10, and vimentin and negative for CK7." (PMID 39851801, 2025). "The tumor cells were positive for CD99 and vimentin but negative for CK and CD45." (PMID 40060231, 2025). "Tumour cells expressed DOG1, c-Kit, α-SMA and vimentin, and were negative to desmin and S-100." (PMID 40045318, 2025). "The immunophenotype of the tumor did not reveal a clear line of origin, with negative staining for GFAP, OLIG2, S100 protein, SOX10, desmin, pankeratin, synaptophysin, and only focally positive vimentin." (PMID 40159593, 2025). "Interestingly, vimentin, a canonical marker of EMT, was predominantly expressed in mesenchymal tissues rather than in the metastatic tumor cells themselves, which are primarily surrounded by capillaries within the nests of metastatic cells." (PMID 40349174, 2025). "The tumor cells in the fallopian tube are diffusely positive for P16 immunostain a surrogate marker for HPV immunostaining, focally weak positive for estrogen receptor, negative for vimentin and shows P 53 as wild type." (PMID 38989238, 2024). "In the IHC study, tumor cells showed positivity for CD99, EMA, vimentin, and TLE1, while they were negative for NKX2.2, WT1, BCOR, PDGFA, cytokeratins, muscle markers (smooth muscle actin, desmin, caldesmon, MyoD1, and myogenin), and melanocytic markers (HMB45, SOX10, and S100)." (PMID 38339014, 2024). "Immunohistochemical staining shows that the tumour cells were positive for CD31, D2‐40, Vimentin, and Factor VIII, while negative for CKAE1/AE3, CK7, CK20, EMA, TTF‐1, Napsin A, Synaptophysin, Chromogranin, CD56, HMB45, PAX8, WT1, CD34, P63, P40, CK5/6, ER, Calretinin, and Desmin." (PMID 39588325, 2024). "Immunohistochemically, the tumor cells were strongly and diffusely positive for CK and CK7, moderately positive for Dog-1, and negative for vimentin, P63, P40, napsin A, thyroid transcription factor 1, chromogranin A, CD56, synaptophysin, S-100, SRY-related HMG-box 10, and PAX8." (PMID 36820581, 2023). "The tumour cells were also positive for GATA3, E-cadherin, Pax-8, Succinate dehydrogenase B (SDHB) and Fumarate hydratase (FH), and negative for vimentin, Carbonic anhydrase 9 (CA9), CD10, P504s, CK20, TFE3, TFEB, HMB45, ALK and Forkhead box protein I1 (FOXI1)." (PMID 36816543, 2023). "In addition, we validated vimentin and WNT5B using immunofluorescence staining in a tumor with EMT tumor cells compared to another tumor without EMT tumor cells." (PMID 36973268, 2023). "All non-TNBC samples showed no vimentin staining within the tumor cells, whereas 78% (n = 40) of all TNBC samples exhibited a positive vimentin staining within the tumor cells (17 (33%) strong positive; 15 (29%) medium positive; 8 (16%) weak positive) and 11 (22%) were negative." (PMID 36769215, 2023). "Although no discernible difference in tumor size was observed across the groups, the shCPEB2 group for SMMC-7721 and MHCC-97L cells had considerably higher E-cadherin levels and lower vimentin levels." (PMID 37514073, 2023).
tumor (continued). "This suggests that lack of vimentin expression does not allow for its EMT function, and tumor metastasis may be promoted through other routes." (PMID 35320951, 2022). "Interestingly, 5 existing markers (ACTA2, VIM, S100A4, POSTN, PDPN) are not specific for any of the 9 tumor types we studied." (PMID 36263012, 2022). "The results showed that MYPT1 overexpression could significantly inhibit the expression of N‐cadherin but not E‐cadherin or Vimentin, which led us to speculate that MYPT1 suppresses tumour metastasis by inhibiting N‐cadherin." (PMID 36106411, 2022). "Furthermore, IHC analysis revealed that the Ki-67 labeling index (LI) was 30–40%, indicating highly proliferative tumor cells, and a large portion of tumor cells strongly expressed Pan-TRK, S-100, and CD34, while negative for vimentin, SOX10, and desmin." (PMID 35572973, 2022). "On IHC, tumor cells expressed RCC, PAX8, CD10 and Vimentin and were negative for CK7 and CK20." (PMID 34034720, 2021). "E-cadherin was substantially detected and vimentin was not apparently detected in tumor sections of mice injected with TMEM52B-expressing control cells, while vimentin but not E-cadherin was moderately detected in tumor sections of mice injected with TMEM52B-suppressed cells." (PMID 33641663, 2021). "Emodin treatment (40 mg/kg, i.p) did not alter the tumor size and weight, but suppressed macrophage infiltration in the tumors (particularly CD206+ M2-like macrophages), increased CD4+ and CD8+ T cells, and decreased the expression of Vimentin and MMP9." (PMID 34073059, 2021). "Cells in non-tumour tissue were non stained for the EMT markers vimentin and β-catenin while MENA was found in a small proportion of cells in non-tumour tissue, and within the tumour tissue approximately 50% of cells were positive for vimentin and β-catenin, and had patchy staining for MENA." (PMID 33906633, 2021). "Finally, tumor cells within residual metastatic foci in the lung did not express the epithelial marker CK8 and acquired expression of the mesenchymal marker vimentin, consistent with an EMT." (PMID 34088357, 2021). "The postoperative pathology showed the tumor cells to be positive for chromogranin, synaptophysin, cytokeratin, CD56 (partial weak), negative for vimentin, CD117, DOG-1, CD34, S-100, SMA, desmin, and Ki-67 approximately 2%, which confirmed the diagnosis of d-NETs." (PMID 33578581, 2021). "All reported cases that used immunohistochemistry techniques to diagnose meningioma observed that the tumor cells stained positive for monoclonal antibodies against EMA and vimentin, with no immunoreactivity for S-100 protein, which was similar to our findings." (PMID 32850120, 2020). "Importantly, in CRC patient tumor sections, we observed a negative correlation between KLF4 levels and mesenchymal markers including TWIST, β-catenin, claudin-1, N-cadherin, and vimentin." (PMID 32566755, 2019). "Additionally, vimentin expression has been correlated with poor survival in RCC patients, though this study did not differentiate between tumor subtypes." (PMID 30863721, 2019). "However, in HNACC SOX2 levels were neither correlated with vimentin nor with E-cadherin expression, further supporting a context dependent regulation and function of SOX2 in distinct tumor entities." (PMID 29596469, 2018). "In 4 of the 5 tumor pairs (#3319, 9036, 1576, 2022), there were no major differences between primary and recurrent tumors, as nearly all cells were positive for GFAP and VIM." (PMID 29152094, 2017).
tumor (continued). "The clinical value of ISET® is predictably related to its capacity to isolate all types of tumor cells including tumor cells in Epithelial to Mesenchymal Transition (EMT), expressing mesenchymal markers such as Vimentin, but not (or barely) expressing epithelial markers (EpCAM or cytokeratin)." (PMID 28060956, 2017). "For example, anti-vimentin staining, which was successfully used to visualize E98FM tumor cells on traditional 5-μm sections, did not result in detection of tumor cells in our iDISCO processed samples, and the CD31 staining was hampered by low signal-to-noise ratio (data not shown)." (PMID 28699046, 2017). "A pathologic examination showed neoplastic tissue composed of pleomorphic cells, while immunohistochemistry of the tumor cells was positive for vimentin and negative for Pan CK, EMA, S‐100, HMB‐45, SM‐actin, desmin, CD 31, CD 34, and CD 68, while 30% of tumor cells showed reactivity to Ki67." (PMID 28588856, 2017). "However, further immunohistochemical staining showed that the tumor cells were negative for HMB45, melan-A and S-100, diffusely positive for vimentin, and focally positive for EMA." (PMID 28438212, 2017). "The tumor cells were diffusely positive for cytokeratin, EMA, and vimentin, and negative for bcl-2." (PMID 27068820, 2016). "To further confirm whether or not HS-173 inhibits tumor growth through the regulation of EMT, we identified the expression levels of Ecadherin, Vimentin, ZEB1 along with p-AKT and p-Smad2." (PMID 27793006, 2016). "Expression level of FCGR1A, although not correlated with VIM or CDH1, had r = 0.31 and r = 0.42 with SNAI1 and SNAI3 respectively, suggesting it may be co-expressed with these EMT drivers in some tumours." (PMID 27876705, 2016). "Biopsy of the nodule and atrophic plaque revealed dense proliferation of spindle-shaped tumor cells from the dermis to the subcutaneous adipose tissue, and positive immunostaining for CD34 and vimentin in addition to negative staining for factor XIIIa and α-smooth muscle actin." (PMID 26932148, 2016). "Immunohistochemically tumor cells usually express CD34 and vimentin but not EMA and S100." (PMID 26090247, 2015). "In this case, the tumor cells were proven chromophobic by Pearse’s PAS stain, showing immunopositivity for PRL, chromogranin-A, and synaptophysin but no immunoreactivity to S-100 protein, vimentin, and GFAP." (PMID 26228535, 2015). "Interestingly, the tumor in this case showed negative staining for EMA and membrane staining for vimentin." (PMID 24955270, 2014). "Diagnosis of metastatic renal cell carcinoma (RCC) was confirmed by immunohistochemical stains, which showed the tumor cells to be positive for CD10, vimentin and pancytokeratin, but negative for CK7, carcinoembryonic antigen (CEA), chromogranin, synaptophysin and CD68." (PMID 23305230, 2013). "Immunohistochemical staining was distinguishable to show that tumor cells of CCRCC diffusely positive for CD10, vimentin and negative for E-cadherin, CK7, CK20, while that of CDC are positive for E-cadherin, CK7, vimentin, partially CD10, and negative for CK20." (PMID 23866935, 2013). "The staining pattern of the malignant cells found in the bone marrow, however, was similar to the epithelial staining pattern observed in Primary Tumor Foci #1-5 with cells staining strongly for CK5, CK8/18 and membranous E-cadherin, but not vimentin (bottom row)." (PMID 23049838, 2012). "The tumour cells showed diffuse immunopositivity for SMA (contractile protein actin) and vimentin (a mesenchymal cell intermediate filament) and negative for desmin (Smooth muscle antigen) and S-100 (nervous tissue antigen) which has been consistently used to spot a myofibroblastic lineage." (PMID 22966474, 2012).